MIR657 (microRNA 657)
Synonyms: hsa-mir-657; MIRN657
Gene: MicroRNA gene on chromosome 17 (81,125,276 to 81,125,373, reverse strand). Ensembl gene ENSG00000207736.
Gene Ontology:
Biological process: miRNA-mediated post-transcriptional gene silencing
Cellular component: RISC complex